AFP (alpha fetoprotein)
Diseases named in the same sentence as AFP in open-access papers (continued):
Sharing a sentence is not in itself a finding about the gene and the disease.
Cirrhosis (continued). "At HCC diagnosis, fewer MAFLD patients had cirrhosis, alpha fetoprotein concentration ≥ 400 ng/mL, tumor size ≥ 5 cm, mulinodular, microvascular invasion, receiving major hepatectomy, and receiving adjuvant transarterial chemoembolization." (PMID 35127490, 2021). "The variables with p<0.10 on univariate analysis (cirrhosis, serum AFP, serum Ang2, and the number of tumors) were subjected to multivariate analysis." (PMID 33854629, 2021). "At the present time, HCC is increasingly recognized at a much earlier stage as a result of the routine screening of patients with known cirrhosis using cross-sectional imaging studies and serum alpha-fetoprotein (AFP) measurements." (PMID 34181338, 2021). "In fact, the AUC for pentraxin to discriminate early HCC from cirrhosis was 0.90, while it was 0.68 for AFP, clearly suggesting the potential of pentraxin 3 as a biomarker for early HCC." (PMID 33918270, 2021). "The 25-lncRNA risk score and other clinicopathological factors, including gender, age, race, cirrhosis, vascular invasion, serum AFP level and TNM stage, were used as covariates." (PMID 34717566, 2021). "In this study, the multivariate analyses revealed that the clinical T stage, age, presence of cirrhosis, AFP levels, and haemoglobin levels were significant independent predictors of OS." (PMID 34126955, 2021). "Next, we examined the prognostic significance of clinical variables, including age, sex, HCV infection, Child-Pugh classification, cirrhosis, serum AFP, serum DCP, serum Ang2, tumor numbers, and the maximal tumor diameter." (PMID 33854629, 2021). "An individual with cirrhosis is considered to be at higher risk of HCC, and increased levels of alpha fetoprotein (AFP) often serves as clinical biomarker for HCC diagnosis, yet its sensitivity is not very promising." (PMID 34094907, 2021). "The high- and low-risk groups differed significantly in histology grade, vascular tumor cell type, AFP, new tumor event after initial treatment, main tumor size, cirrhosis, TNM stage, BCLC stage, and CLIP score." (PMID 34869350, 2021). "The mRNA expression of ACE2 was related to some clinical parameters of the HCC patients, containing age, AFP level and cirrhosis." (PMID 34369278, 2021). "Of significance, the statistical analysis of the data found seven haptoglobin N-glycopeptides that can be used alone, combined with AFP, or combined themselves, to better differentiate between cirrhosis and HCC group samples than previous approaches." (PMID 34436504, 2021). "Other variables, including MELD score, hepatitis C virus (HCV) cirrhosis, alcoholic cirrhosis, AFP, downstaging therapy, and type of liver graft (uDCD/DBD), did not influence patient survival." (PMID 34188156, 2021). "The results demonstrated that the combination of N-glycopeptides, either with AFP or between themselves, considerably enhanced the accuracy of the differentiation of the cirrhosis and the HCC sample groups." (PMID 34436504, 2021). "Meanwhile, the baseline data of the patients, such as gender, age, AFP, and background of cirrhosis, are also important references." (PMID 34154624, 2021). "The closest points between two cohorts corresponds to samples in the early HCC stage and the cirrhosis samples with the highest AFP (alpha-fetoprotein) levels, which is glycoprotein used for the detection of HCC." (PMID 34436504, 2021). "For the differentiation of HCC vs. Cirrhosis, the use of circSMARCA5 brought an AUC of 0.711, and this value increased to 0.858 when combined with AFP." (PMID 34944400, 2021). "Following univariate analysis, the waitlist length (p = 0.009), AFP value at transplant (p = 0.001), and the cirrhosis etiology (p = 0.008) emerged as possible predictors of HCC recurrence; HCV etiology was not a predictor." (PMID 34885087, 2021). "Diseases such as HCC, cirrhosis, yolk cystic tumor, and teratoma cannot be considered alone in patients with elevated serum AFP levels." (PMID 34956891, 2021).
Cirrhosis (continued). "By contrast, the HCC group had more patients with old age, male, cirrhosis, Edmondson–Steiner grades I-II, tumor number, AFP level ≥ 200 ng/mL, ICG%, operative margin > 1 cm, macrovascular invasion, and antiviral therapy." (PMID 33413162, 2021). "In 2012, a 72-year-old Caucasian man with Child-A cirrhosis, due to prior chronic active hepatitis C and type 2 diabetes, was referred for un unexpected increase of AFP (563 ng/mL) five years after successful treatment of HCV with peg-interferon and ribavirin." (PMID 33922938, 2021). "Recently, it was shown that the combination of increased ALT, AFP, presence of cirrhosis, and higher MELD score (model for end-stage liver disease) are determinants for the time to development of HCC." (PMID 33066136, 2020). "Our univariate and multivariate analysis revealed that abnormal serum ALT, AST, AFP level, NLR and age, sex, cirrhosis, HBeAg+, or therapy were all individual independent risk factors for HBV‐HCC." (PMID 32150664, 2020). "A large proportion of the patients had elevated AFP levels (64.9%) and cirrhosis (69.5%), and 46.6% of patients underwent tumor resection surgery." (PMID 33288828, 2020). "Still, it appears that metabolomic biomarkers perform statistically better comparing with AFP in discriminating HCC from cirrhosis or HCC from healthy volunteers." (PMID 32443747, 2020). "Our aim was to investigate AFP, PIVKA-II and GPC-3 diagnostic accuracy for the detection and the prediction of HCC development in patients with cirrhosis of viral etiology under surveillance." (PMID 33142893, 2020). "In the HALT-C trial that included over 1000 HCV+ patients with moderate to severe fibrosis, 11% and 27% of patients with bridging fibrosis or cirrhosis had AFP values above 20 ng/mL, respectively." (PMID 32492896, 2020). "History of hepatitis or cirrhosis, and higher serum alpha‐fetoprotein (AFP) level were indicators for malignant lesions, while liver parasites and higher body temperature were indicators for inflammatory lesions." (PMID 32017229, 2020). "Compared with other non-invasive indicators, the predictive performance of WFA+-M2BP was similar to HA and FibroScan in assessing cirrhosis, but was equivalent to AFP in HCC." (PMID 32601332, 2020). "This study found that serum levels of miR‐363‐5p and miR‐765 in patients with AFP‐NHCC were significantly higher than those in cirrhosis and controls and were related to differentiation, tumor size, and TNM stage, confirming that they are oncogenes in HCC." (PMID 31693242, 2020). "Clinicopathological factors, such as sex, age, AFP, cirrhosis, Child-Pugh stage, tumor histologic grade, AJCC stage, and surgical margin status, were included in the nomogram." (PMID 31998802, 2020). "In the presence of cirrhosis, serial monitoring by AFP and imaging every 6 months should be recommended similar to patients with HCV74." (PMID 33303924, 2020). "The purpose of this study was to determine the predictive value of the AFP model in Chinese hepatitis B virus (HBV)–related cirrhosis HCC patients." (PMID 32974380, 2020). "In this study of LT for HCV-cirrhosis, preoperative AFP levels and the number of PRBCU transfused during surgery were associated with overall survival, whereas microvascular invasion with HCC recurrence." (PMID 33134370, 2020). "Regarding AFP ROC curve to differentiate cirrhosis from HCV, at the cut-off value of 10.0 ng/ml, serum AFP showed sensitivity of 70% and specificity of 100% with AUC of 0.944 (p < 0.001, 95% CI 0.868- 1.000)." (PMID 32102538, 2020). "The characteristics associated with clinical prognostic outcome, including tumor size, multinodular, cirrhosis, serum AFP level, and tumor stage, were included in the multivariate cox regression analysis." (PMID 32596342, 2020). "The AUSROC of WFA+-M2BP was equivalent to HA and FibroScan for assessing cirrhosis, and similar to AFP for diagnosing HCC." (PMID 32601332, 2020).
Cirrhosis (continued). "Performance of the APRI score in diagnosis of cirrhosis and AFP in the diagnosis of HCC was determined using AUROC analysis." (PMID 33357229, 2020). "The investigated variables were sex, cirrhosis, AFP, modified UICC stage, E-S grade, vascular invasion, and expression levels of FGFR2, VEGF, TRAIL-R1, and TRAIL-R2." (PMID 31940413, 2020). "On the other hand, AFP levels are often elevated in patients with chronic liver diseases, such as hepatitis and cirrhosis." (PMID 32736604, 2020). "The median value of the serum AFP level was 4.0 ng/mL, 4.2 ng/mL, 38.6 ng/mL, and 43.2 ng/mL in the cirrhosis group with a normal ALT level, 1 upper limit of normal (ULN) < ALT level ≤ 2 ULN, 2 ULN < ALT level ≤ 5 ULN, and ALT level > 5 ULN, respectively." (PMID 33490235, 2020). "On some occasions, other diseases, such as hepatitis, cirrhosis, colorectal cancer and lung cancer, also present with elevated AFP." (PMID 33372599, 2020). "We propose to evaluate the conditions for increasing the AFP value in patients with compensated cirrhosis and chronic C virus infection, given that, in this case, studies claim that most of these patients do not necessarily associate HCC." (PMID 32341704, 2020). "For analysis of combination of AFP and let-7a-1, a positive result of at least one marker (AFP and /or let-7a-1) was considered to indicate liver cirrhosis, which improved sensitivity to detect cirrhosis to become 95%." (PMID 32102538, 2020). "Although there is no consensus on the surveillance of patients with FALD, serial monitoring of the alpha fetoprotein level and imaging at 6-month intervals is required in patients with cirrhosis." (PMID 33303924, 2020). "The diagnostic accuracy of AFP, PIVKA-II and GPC-3 for the discrimination between patients with cirrhosis and those with HCC was assessed by receiver operating characteristic (ROC) curve analysis." (PMID 33142893, 2020). "AFP tests for cohort 2 showed a gradual increase of AFP in human serum from chronic hepatitis to cirrhosis and HCC, with a similar increase in anti-ATIC response." (PMID 33352757, 2020). "Serum miR‐363‐5p, miR‐765, and PIVKA‐II levels were significantly higher in AFP‐HCC patients than in cirrhosis and controls." (PMID 31693242, 2020). "In particular, DCP was reported to showcase higher sensitivity and specificity in distinguishing HCC from other chronic liver diseases, including cirrhosis, when compared to AFP." (PMID 32443747, 2020). "Subgroup analysis showed that the pooled sensitivity and specificity of AFP+AFP-L3%+DCP in the diagnosis of HCC versus cirrhosis patients were 0.81 and 0.82, respectively." (PMID 33015170, 2020). "Serum miR‐765 was significantly increased in patients with AFP‐HCC (183.1 ± 22.6) compared with cirrhosis (144.0 ± 18.9) and controls (142.9 ± 19.6, P < .05)." (PMID 31693242, 2020). "It has been shown that metabolite-based biomarkers can distinguish HCC from cirrhosis better than the conventional marker, alpha-fetoprotein (AFP)." (PMID 32344559, 2020). "An increase in the number of postoperative CTCs when compared to the number of preoperative CTCs is associated with lower survival and higher recurrence among patients with low AFP levels and cirrhosis." (PMID 32071283, 2020). "In order to enhance the ability of AFP to detect HCC developed on cirrhosis, we attempted to combine AFP with conventional clinical metrics to develop a simple and effective method for identifying cirrhotic patients with complicating HCC at various AFP levels." (PMID 32038998, 2019). "When we combined both microRNA-215 and AFP to discriminate between control and cirrhosis groups, the ROC analysis showed 76.0% sensitivity, 81.7% specificity at the best cutoff value of ≥ 0.56." (PMID 31554369, 2019).
Cirrhosis (continued). "In the stratification of HLA-A for RFS analysis, high expression showed significance in males, age > 60 years, chronic HBV carriers, tumour size > 5 cm, cirrhosis, low AFP levels (≤ 300 ng/ml) and C stage of the BCLC system compared with low expression." (PMID 31602270, 2019). "Meanwhile, a log-rank analysis demonstrated that patients with cirrhosis, multiple tumor, vascular cancer embolus, AFP> 8.54 ng/mL, ALP>146U/L and APTT>28.1s had a reduced probability of postoperative survival." (PMID 31531530, 2019). "Multivariate Cox analysis in the training cohort showed that preoperative ultrasound cirrhosis, AFP, BCLC stage, HBV DNA, and tumor size were independently associated with OS." (PMID 31179237, 2019). "We next performed a multivariate Cox proportional hazards regression analysis comprised of univariate variables with a p < 0.05, which included the NDMT signature status, stage, cirrhosis status and alpha-feto protein (AFP) levels of >400 ng/ml." (PMID 30833661, 2019). "The cut-off value of AFP for discriminating HCC patients versus cirrhosis and control groups was 8.9 ng/mL." (PMID 31554369, 2019). "Mild to moderate elevation in AFP is sometimes found in patients with hepatitis or cirrhosis, but severe elevation of AFP to levels of 200 ng/mL or more is likely to be caused by HCC with high malignant potential." (PMID 31850221, 2019). "A panel consisting of miRNA-122-5p + miRNA-486-5p + miRNA-142-3p distinguished HCC from cirrhosis (AUC = 0.94; sensitivity = 80%, specificity = 95%; p < 0.001), outperforming AFP (AUC = 0.64, p = 0.065)." (PMID 30781550, 2019). "We found a significantly higher levels of AFP in HCC patients (median= 294.9 ng/mL) compared to the cirrhosis patients (median= 19.5 ng/mL) and control group (median= 4.3ng/mL)." (PMID 31554369, 2019). "The panel distinguished HCC from cirrhosis and normal controls, with an area under the receiver operating curve (AUC) of 0.82; this was significantly better than that of AFP (AUC: 0.75)." (PMID 31590436, 2019). "Univariate analysis showed that APGA, APRI, FIB-4, FibroQ, GUCI, King's score, Lok index, PAPAS, cirrhosis, number of tumors, vascular cancer embolus, AFP, ALP and APTT were significantly related to prognosis." (PMID 31531530, 2019). "The meta-regression analysis categorized by age, AFP, proportion of cirrhosis, proportion of larger tumour size, proportion of tumour encapsulation, and TNM stage was not achieved and was attributed to the lack of data in the included studies." (PMID 30718977, 2019). "In the univariate analysis, old age (>60 years old), HCV infection, HBV and HCV coinfection, diabetes mellitus, cirrhosis, microvascular infection, high AFP (>5 μg/L), high NLR (>1.8), low PNI (≤45), and low SII (160 × 109/L) were associated with poor OS." (PMID 31614976, 2019). "In summary, MK is an adequate diagnostic biomarker that is generally more sensitive than AFP for the discrimination of HCC patients from normal individual and cirrhosis, CHC, CHB, GIT, BLT and BGID patients." (PMID 31600291, 2019). "Three hundred and sixty‐eight HCC patients from the TCGA were divided into several subgroups according to their clinical features such as race, gender, age, hepatitis virus infection, alcoholic liver, cirrhosis, and serum AFP level." (PMID 31674731, 2019). "In newly developed cirrhosis associated with hepatitis B virus (HBV), the levels of ALT, AFP, and HBV markers as well as age were predictors for HCC development." (PMID 32038998, 2019). "Human cirrhotic and cirrhosis-associated HCC tissues showed an increase of IMP2 expression and of the progenitor cell markers SOX9, SPP1/osteopontin, CDH1/E-cadherin, AFP, PROM1/CD133, BEX1, EPCAM." (PMID 31555647, 2019). "AFP is a glycoprotein belongs to the albumin family,which does not express or underexpress on normal liver tissues, but the AFP level was increased significantly on hepatitis or cirrhosis tissues and the highest expression on liver cancer tissues." (PMID 31827599, 2019).
Cirrhosis (continued). "Tumour size, cirrhosis, AFP and BCLC stage showed significance in OS (P = 0.002, 0.041, 0.049 and < 0.0001, respectively)." (PMID 31602270, 2019). "Before PSM, patients in the RFA group were significantly older, had a higher proportion in the 0–30 mm tumor size, a higher level of AFP and were more likely to be classified as having cirrhosis compared to those in the HR group." (PMID 30863723, 2019). "The univariate analysis showed that poor RFS was also associated with old age (>60 years old), HCV infection, HBV and HCV coinfection, diabetes mellitus, cirrhosis, microvascular invasion, high AFP (> 5 μg/L), low PNI (≤45), and SII (≤160 × 109/L)." (PMID 31614976, 2019). "There were significant differences in sex, platelet count, AFP level, the presence of cirrhosis, and number of curative treatments for HCC before the DAA therapy between the patients with and without HCC recurrence after the DAA therapy." (PMID 30900818, 2019). "But serum AFP mRNA can be detected during pregnancy, and in patients with acute hepatitis, chronic hepatitis, cirrhosis and other cancers." (PMID 31068623, 2019). "Except for AFP, the status of fibrosis or cirrhosis is also a useful predictor for HCC prognosis, which includes the Ishak stage and liver stiffness measurement." (PMID 31885547, 2019). "Cox regression analysis demonstrated a correlation between cirrhosis and HBsAg (p < 0.001), AFP (p = 0.026), and tumor dimension (p < 0.001)." (PMID 31029128, 2019). "As expected, serum AFP levels were significantly higher in the HCC group than in the cirrhosis and control groups." (PMID 31590436, 2019). "Independent predictors of HCC among all cirrhosis etiologies included: age, male sex, Hispanic ethnicity, high serum alpha fetoprotein, alkaline phosphatase and AST/√ALT ratio and low serum albumin and platelet count." (PMID 30260995, 2018). "With the exception of the p-value for AA and EA combined, AFP was unable to distinguish HCC from cirrhosis in AA (Panel B and B1) or EA (Panel C and C1), emphasizing the need for more potent HCC markers particularly for subjects with HCV+." (PMID 29538406, 2018). "The positive ratios of Twist+ CTCs correlated with portal vein tumor thrombi, TNM staging, AFP, cirrhosis, tumor number, tumor size, and microvascular invasion." (PMID 30046595, 2018). "Current VA good practice guidelines recommend regular surveillance testing with ultrasonography and AFP at 6–12 month intervals in patients with cirrhosis." (PMID 29301497, 2018). "Comparison of each of these three HCC subgroups with cirrhotic patients revealed significantly higher AFP (p = 0.000) and IL-6 (p = 0.000) levels in each subgroup, as compared with cirrhosis cases." (PMID 29963457, 2018). "A population-based US cohort study found that among HCC patients with a prior diagnosis of cirrhosis who received regular surveillance, 52% received both ultrasonography and AFP, 46% received AFP alone and 2% received ultrasonography alone." (PMID 29301497, 2018). "The PEB algorithm has been applied to serial AFP data from the Hepatitis C Antiviral Long-term Treatment against Cirrhosis (HALT-C) trial." (PMID 29301497, 2018). "Analysis of the derivation cohort revealed that patients who received dynamic CT (n = 429) showed older age, higher frequency of live cirrhosis, higher AFP levels and more advanced liver disease compared to patients without dynamic CT (n = 744)." (PMID 29293612, 2018). "Along with that, we didn’t observe any significant differences between groups regarding serum albumin, serum bilirubin, serum AFP, tumour numbers, tumour size, tumour stage, cirrhosis, HBsAg, HCV, ICG clearances." (PMID 29212179, 2017). "The stratified analysis also revealed that high PLCE1 expression increased the risk of recurrence and death in patients who were male and had early-stage BCLC, a single tumor, cirrhosis, and AFP level > 300 ng/ml." (PMID 28418898, 2017).